LAMP2 (lysosome associated membrane protein 2)
Diseases named in the same sentence as LAMP2 in open-access papers (continued):
Sharing a sentence is not in itself a finding about the gene and the disease.
glioblastoma (5 papers, 2016 to 2025). The most malignant astrocytic tumor (WHO grade IV). "A strong upregulation of LC3B, p62, LAMP2 and CTSB was detected in perinecrotic areas in glioblastomas suggesting micro-environmental changes as a driver of autophagy induction in gliomas." (PMID 26956048, 2016). "Highest LC3B (5A*), p62 (5B*), LAMP2 (5C*) and CTSB (5D*) levels were seen in close vicinity of pseudopalisading necrosis in human glioblastomas, frequently decreasing within a 100–500 μm distance from the border of the pseudopalisading cells." (PMID 26956048, 2016). "In conclusion, BIBF inhibits autophagy and promotes the accumulation of toxic substances in glioblastoma, leading to the onset of apoptosis by decreasing the expression levels of LAMP1, LAMP2, and Rab7 while impairing lysosomal function and its ability to fuse with autophagosomes." (PMID 39859159, 2025). "Concerning the classic lysosomal markers LAMP2 and CTSB no considerable differences were observed in LAMP2 protein and RNA expression, while slightly higher CTSB protein levels were detected in glioblastoma tumor centers compared to normal CNS tissue and infiltration zones." (PMID 26956048, 2016).
glioma (5 papers, 2016 to 2022). A benign or malignant brain and spinal cord tumor that arises from glial cells (astrocytes, oligodendrocytes, ependymal cells). "We then investigated key autophagosomal (LC3B, p62, BAG3, Beclin1) and lysosomal (CTSB, LAMP2) molecules in 350 gliomas using immunohistochemistry, immunofluorescence, immunoblotting and qPCR." (PMID 26956048, 2016). "LAMP2 was found to be overexpressed in the perinecrotic areas of gliomas." (PMID 34568059, 2021). "The intra-tumoral distribution of CTSB and LAMP2 nicely paralleled the heterogeneity of p62 and LC3B indicating that central constituents of the ALN are present in similar areas in human gliomas thereby allowing for the functioning of the entire autophago-lysosomal degradation complex." (PMID 26956048, 2016). "Finally, the results further confirmed the differences in LAMP2 expression between the tissues of five tumor types and the corresponding normal tissues from THPA and showed that LAMP2 was significantly highly expressed in gliomas, BLCA, BRCA, OV, and KIRP." (PMID 35530327, 2022).
glomerulonephritis (5 papers, 2013 to 2024). A renal disorder characterized by damage in the glomeruli. "In fact, autoantibodies directed against LAMP-2 (anti-LAMP-2) are frequently detected in both MPO and PR3-ANCA-associated glomerulonephritis, as well as in ANCA(−) glomerulonephritis." (PMID 36294902, 2022). "A study on the origin and development of ANCA-associated glomerulonephritis with LAMP-2 and LAMP-2 ANCA suggested that infection and molecular mimicry may trigger autoimmunity by inducing antibodies to bacterial adhesion protein FimH and the development of AAV." (PMID 25648906, 2015). "Furthermore, while LAMP2 showed no homology with MPO or PR3 (thus excluding synergy with the anti-idiotype hypothesis), it showed significant similarity to the sequence of the bacterial protein FimH, which could induce both LAMP2-IgG and a pauci-immune glomerulonephritis on immunisation of WKY rats." (PMID 25056155, 2014). "This protein has a close similarity with the adhesive protein FimH, expressed on the surface of the gram-negative bacteria, and these antibodies, both LAMP-2 and FimH can produce glomerulonephritis in animal models." (PMID 38736966, 2024).
multiple myeloma (5 papers, 2014 to 2025). "A previous study demonstrated that SORT1/LAMP2-mediated extracellular vesicle secretion and cell adhesion resulted in lenalidomide resistance in multiple myeloma." (PMID 40750784, 2025). "Bortezomib, a proteosome inhibitor used in the treatment of multiple myeloma, induced the colocalization of LC3 and Lysosome Associated Membrane Protein 2 (LAMP2), a lysosome marker, in NCI-H929 cells by immunofluorescent microscopy." (PMID 39082334, 2024). "Further understanding of the functions of LAMP2 and its pathways in myeloma pathogenesis is important to elucidate whether lysosomal disruption could be a novel therapeutic strategy for the treatment of MM patients with LAMP2 over-expression and lysosomal abnormalities." (PMID 24690091, 2014).
periodontitis (5 papers, 2017 to 2020). An acute or chronic inflammatory process that affects the tissues that surround and support the teeth. "It has been shown that LAMP-2-/y mice are liable to develop oral infections that cause periodontitis." (PMID 32854285, 2020). "In this context, LAMP-2-deficient mice, a key protein for the autolysosome’s formation, developed severe periodontitis in the early stages of life." (PMID 32423042, 2020).
atherosclerosis (4 papers, 2016 to 2023). A disease characterized by the build-up of fatty material and calcium deposition in the arterial wall resulting in partial or complete occlusion of the arterial lumen. "Deficiencies in LAMP2 levels, and, thus, the autophagy-lysosomal system, lead to autophagy and vascular homeostasis impairments, resulting in disease progression, including atherosclerosis and cardiac defects." (PMID 34360560, 2021). "To investigate the impact of IL11 expression on aortic inflammation, we probed for galectin-3 (LGALS3) and lysosome-associated membrane protein-2 (LAMP2) expression which are known markers for macrophages but also rarely expressed in VSMCs in response to atherosclerosis or injury." (PMID 33082445, 2020).
gastric cancer (4 papers, 2013 to 2023). A primary or metastatic malignant neoplasm involving the stomach. "Lamp2 protein levels increased 2.0-fold in poorly differentiated human gastric carcinomas, compared with normal tissues." (PMID 24527069, 2014). "Because the ANXA4 expression in AGS gastric cancer cells induces expression of membrane proteins RHAMM and LAMP2, we examined the expression of these proteins in OVISE and OVTOKO cells." (PMID 24244679, 2013).
hepatocellular carcinoma (4 papers, 2018 to 2023). A malignant tumor that arises from hepatocytes. "Increased LAMP2 expression is observed in poorly differentiated human gastric adenocarcinoma, hepatocellular carcinoma, salivary adenoid cystic carcinoma, and invasive prostate carcinoma, as well as in patients with esophageal squamous cell carcinoma." (PMID 33322704, 2020). "However, little is known about the role of Lamp2 in hepatocellular carcinoma (HCC) metastasis." (PMID 30100986, 2018).
Hyperglycemia (4 papers, 2018 to 2025). An increased concentration of glucose in the blood. "Studies in αTC1-6 cells — a model of α cells — show that, under chronic hyperglycemia, glucagon granules misroute from degradative LAMP2+ lysosomes to LAMP1+ secretory lysosomes, contributing to hypersecretion." (PMID 41026524, 2025). "Moreover, α cells exposed to hyperglycemia showed that glucagon degradation at LAMP2+ lysosomes is reduced, with increased redirection to secretory LAMP1+ lysosomes." (PMID 41026524, 2025). "Given that TFEB nuclear translocation and LAMP2 expression are suppressed in the islets of T2D, we hypothesized that hyperglycaemia and hyperlipidaemia may inhibit TFEB nuclear translocation and autophagy." (PMID 30710421, 2019).
Hypertension (4 papers, 2021 to 2024). The presence of chronic increased pressure in the systemic arterial system. "For example, in NAFLD, myocellular autophagy is enhanced as a metabolic response to hyperammonemia, or in animals with hypertension, autophagy markers, including LC3I, ATG7, and lysosome-associated membrane protein 2 (LAMP2), are increased in skeletal muscle." (PMID 37876013, 2023).
neuroblastoma (4 papers, 2012 to 2020). Neuroblastoma (NB) is the most common solid, extracranial childhood tumor. "By performing co-immunostaining for LC3 (green) and LAMP-2 (red) we revealed high amounts of enlarged lysosomes in PON-treated neuroblastoma cells, whereas in DMSO-treated (control condition) cell cultures, lysosomes appeared as smaller punctuate structures." (PMID 32962733, 2020). "Thus, we assessed a potential accumulation of these substrates, due to the lack of the CMA receptor LAMP-2A, through analysis of brain lysates from knockout animals as well as in vitro after stable knockdown of LAMP-2 in murine neuroblastoma cells (N2a)." (PMID 25637286, 2015). "Detection of LAMP-2 protein levels and positioning allowed us to monitor the autophagosome–lysosome fusion process in PON-treated neuroblastoma cells." (PMID 32962733, 2020). "The absence of LAMP-2 did not apparently affect MA or steady-state levels of selected CMA substrates in brain or neuroblastoma cells under physiological and prolonged starvation conditions." (PMID 25637286, 2015). "In neuroblastoma cells treated with PON, the observed changes in both LC3-II and p62 protein levels were indicative of a dose-dependent activation of autophagy, and PON treatment triggered a formation of LC3/LAMP-2-positive autophagic vesicles in the cell cytosol." (PMID 32962733, 2020). "Furthermore, absence of LAMP-2 did not affect CMA substrate levels in brain tissue and in neuroblastoma cells." (PMID 25637286, 2015).
acute myeloid leukemia (3 papers, 2014 to 2024). Acute myeloid leukemia (AML) is a group of neoplasms arising from precursor cells committed to the myeloid cell-line differentiation. "Coincidently, in hematological diseases such as myelodysplastic syndrome (MDS) and acute myeloid leukemia (AML), LAMP2 has also been strongly associated with drug resistance and prognosis." (PMID 37986192, 2023). "De-regulation of LAMP2 was detected in acute myeloid leukemia (AML)." (PMID 24690091, 2014).
astrocytomas (3 papers, 2016 to 2021). "If ApoD targeting to lysosomes is regulated by oxidative stress, we wondered why there is a significant colocalization of ApoD with Lamp2 in 1321N1 astrocytoma cells under control conditions." (PMID 28182653, 2017). "We analyzed 350 astrocytomas for autophagy-associated markers LC3B, p62, BAG3, Beclin1 and the lysosomal markers LAMP2 and Cathepsin B (CTSB) to investigate whether also the lysosomal machinery is altered." (PMID 26956048, 2016).
breast tumors (3 papers, 2015 to 2022). "We also stained breast tumour xenografts from Severe Combined Immune-Deficiency (SCID) mice (immunodeficient mice that have impaired ability of making T or B lymphocytes) for LAMP2 and S100A6." (PMID 26658462, 2015). "For instance, cancer cells in the glandular lumen of breast tumors translocate more LAMP2 to the outer surface of the membrane as an adaptative mechanism to acidosis due to low vascularization." (PMID 35159353, 2022). "Within the group of glycoproteins found to be deregulated in the present study, it was found that LAMP2 overexpression in breast tumors promotes cancer cell survival via chaperone-mediated autophagy (CMA)." (PMID 33182810, 2020). "The mRNA expression level of LAMP2 in breast tumours was significantly higher in cancers than in normal breast or other tissues (note log scale)." (PMID 26658462, 2015).
Cerebral ischemia (3 papers, 2017 to 2022). Restriction of arterial blood supply to the brain associated with insufficient oxygenation to support the metabolic requirements of the tissue. "Moreover, miR-207 reduced the number of cellular lysosomes and autophagosomes and increased the number of autophagic vacuoles by downregulating lysosomal-associated membrane protein 2 (LAMP2), which attenuated cerebral ischemia mainly via affecting mitochondria-induced apoptosis." (PMID 32670010, 2020).
crescentic glomerulonephritis (3 papers, 2021 to 2023). A histopathologic term for a pattern of diseases characterized by extensive crescent formation in the glomeruli; patients present clinically with rapid deterioration of renal function, and possible progression to end-stage renal failure within weeks or months. "Lysosomes have reached fame in nephrology with the discovery that antibodies to a bacterial antigen can cross-react to a previously characterized antineutrophil cytoplasmic antigen (ANCA), namely LAMP2 to cause pauci-immune necrotizing and crescentic glomerulonephritis." (PMID 33433692, 2021). "The involvement of anti-LAMP2 autoantibodies remains controversial in crescentic glomerulonephritis because of the absence of confirmatory data from other groups regarding their high prevalence and their pathogenicity." (PMID 33433692, 2021).
diabetic cardiomyopathy (3 papers, 2023 to 2025). Diabetic cardiomyopathy is a disorder of the heart muscle in people with diabetes. "In our study, the expression of LC3II and P62 was increased, whereas the expression of beclin 1, LAMP2, and cathepsin D was inhibited in the myocardium during diabetic cardiomyopathy and in PA-induced NMCMs." (PMID 37658156, 2023). "Additionally, CREG1 is an important cardioprotective factor, inhibiting FBXO27 expression to prevent LAMP2 protein degradation, promoting autophagy in cardiomyocytes, and alleviating diabetic cardiomyopathy." (PMID 39639394, 2024).
dilated cardiomyopathy (3 papers, 2018 to 2024). Cardiomyopathy which is characterized by dilation and contractile dysfunction of the left and right ventricles. "We present the case of a patient with dilated cardiomyopathy caused by a novel mutation in the lysosome-associated membrane protein-2 (LAMP-2) gene." (PMID 29637036, 2018).
HIV-1 infection (3 papers, 2009 to 2024). The type species of lentivirus and the etiologic agent of acquired immunodeficiency syndrome (AIDS). "To visualize cathepsin B within lysosomes before and after HIV-1 infection, we performed double-immunofluorescence studies of cathepsin B and the lysosomal-associated membrane protein 2 (LAMP2) by in situ PLA co-localization assay." (PMID 22693552, 2012). "Downregulated LAMP2 was further confirmed in resting CD4+ T cells from patients with latent HIV-1 infection." (PMID 38750478, 2024).
Stroke (3 papers, 2015 to 2025). Sudden impairment of blood flow to a part of the brain due to occlusion or rupture of an artery to the brain. "After experimental stroke, we observed increased expression of the lysosomal marker, LAMP2, associated with RPM and MZM and the presence of CD11b+ macrophages within the WP." (PMID 29872438, 2018). "Gene expression data indicated that deficits in antigen presentation were unlikely to be associated with deficits in phagocytosis or the ability to generate peptide antigen via processing by cathepsins as genes associated with these processes (Lamp2, Ctsl) were upregulated after experimental stroke." (PMID 29872438, 2018). "Splenic expression of Lamp2 but not Lamp1 was increased after experimental stroke and analysis of mRNA levels by RT-qPCR confirmed significant upregulation of Lamp2 2 days after experimental stroke in comparison to sham surgery." (PMID 29872438, 2018). "TBM in the follicle are important for phagocytosing apoptotic lymphocytes from the GC reaction and consistent with this showed high levels of LAMP2 immunolabelling in naïve and sham-operated animals, which was marginally increased by experimental stroke." (PMID 29872438, 2018). "Increased expression of LAMP2 immunolabelling was specifically associated with RPM and MZM but remained relatively unchanged in MMM showing a subset-specific increase in lysosome activity after experimental stroke." (PMID 29872438, 2018). "Moreover, the Hsc70 and LAMP2 protein levels demonstrated an up-regulation at the intermediate stage (15 days) post-stroke, although these levels remained unchanged at 30 days." (PMID 26042033, 2015). "Given the increased expression of genes associated with lysosome activity and proteolytic processing and the increased LAMP2 staining in MZM, we next determined if there were any impairments in antigen trafficking from the MZ to the WP after experimental stroke." (PMID 29872438, 2018). "In accordance with the function of TBM in the clearance of apoptotic cells from the follicle, high levels of LAMP2+ immunolabelling co-localized with MOMA-2+ cells in the WP of naïve and sham-operated animals and a small increase was detected 2 days after experimental stroke." (PMID 29872438, 2018). "However, image analysis showed LAMP2 co-localization was significantly increased in both F4/80hi CD11b−/lo and F4/80+ CD11b+ subsets of RPM and MARCO+ MZM 2 days after experimental stroke." (PMID 29872438, 2018).
systemic vasculitis (3 papers, 2020 to 2024). "LAMP-2 has also been detected in adults with AAV-associated renal disease, with moderate to high LAMP-2 titres also found in 35% of paediatric systemic vasculitis cases involving small-medium vessels, with the highest concentrations in MPO- or PR3-positive individuals." (PMID 39769465, 2024). "LAMP-2-ANCA (>1,000 ng/ml) were detected in 35% (n = 18) of pediatric systemic vasculitis patients, of which, 10 (20% of all patients) were found to have high positive titers (>1,500 ng/ml)." (PMID 33613565, 2020).
type 2 diabetic (3 papers, 2013 to 2023). "For example, decreased lysosomal-associated membrane protein 2 (LAMP2) expression has been observed in the myocardium of type 2 diabetic mice, along with increased cardiomyocyte apoptosis." (PMID 36742461, 2023). "Thus, it reverses the changes observed in PBMCs from type 2 diabetic patients, who are characterized by down-regulation of MFN2, PINK1, PARKIN, and LAMP-2 genes at the mRNA and protein level." (PMID 30356025, 2018).
viral infection (3 papers, 2011 to 2024). "LAMP2 regulates lysosome biogenesis and autophagosome maturation in other viral infections such as African swine fever virus (ASFV) by interacting with ASFV E248R and E199L proteins and DENV infections." (PMID 36680137, 2022). "Nevertheless, the mRNA levels of two other LAMP protein family members, LAMP1 and LAMP2, were not altered at any time points indicated, suggesting that LAMP3 may be specifically stimulated by viral infection." (PMID 21810281, 2011).
Acidosis (2 papers, 2015 to 2021). Abnormal acid accumulation or depletion of base. "However, we noticed Lamp2 positivity in correspondence with LD accumulation in spheroids grown in neutral conditions, confirming lipid accumulation only in the presence of the development of intra-spheroid acidosis." (PMID 33467731, 2021).
acute pancreatitis (2 papers, 2022 to 2024). An acute inflammatory process that leads to necrosis of the pancreatic parenchyma. "Depletion of LAMP1 and LAMP2 during acute pancreatitis was reported and suggested as the mechanism responsible for the disruption of the autophagic flux, vacuolisation, and progression of acute pancreatitis." (PMID 36010591, 2022). "Furthermore, mice with deficiency in lysosome-associated membrane protein 2 (LAMP-2) spontaneously developed increased levels of mature trypsin and histopathologic injury characteristic of acute pancreatitis accompanied by impaired autophagy of the exocrine pancreas." (PMID 38709385, 2024).
asthma (2 papers, 2014 to 2024). "There is also little information about the role of LAMP2 in asthma; however, it was recently linked with this disease but not with the phenotypes." (PMID 38542471, 2024). "According to our data, LAMP2 could segregate mixed granulocytic from paucigranulocytic asthma." (PMID 38542471, 2024). "Among the disease-specific genes that were induced in allergic rhinitis patients with or without asthma but not in healthy controls, there were genes (ERAP1, LAMP2) that have been shown to be involved in antigen presentation." (PMID 24475887, 2014).
autoimmune disease (2 papers, 2023 to 2024). A disorder resulting from loss of function or tissue destruction of an organ or multiple organs, arising from humoral or cellular immune responses of the individual to their own tissue constituents. "Studies have demonstrated that anti-LAMP-2 antibodies are useful for the differential diagnosis of vascular injury in autoimmune diseases." (PMID 39044159, 2024).